EGFR (epidermal growth factor receptor)
Diseases named in the same sentence as EGFR in open-access papers (continued):
Sharing a sentence is not in itself a finding about the gene and the disease.
tumor (continued). "In accordance, the malignant lesion can secrete various factors such as bFGF, TGF-β, PDGF, EGF creating tumor microenvironment by interacting through other growth factors receptors (EGFR)." (PMID 29499765, 2018). "Tyrosine kinase inhibitors (TKIs), such as erlotinib, gefitinib and afatinib have been developed to selectively inhibit EGFR tyrosine kinase activity, and in turn, prevent tumour growth and increase tumour cell apoptosis." (PMID 29587666, 2018). "Inhibition of tumor growth by blocking ligand binding to EGFR is one of the mechanisms of action of approved EGFR targeting antibodies." (PMID 30323890, 2018). "High expression of all investigated PDGF family members correlated to increasing NHG and high Ki67, and also to different degrees to TNBC, expression of cytokeratin 5/6 (CK5/6+), young age (< 50 years), large tumour size, ER−, PR− and EGFR+." (PMID 29380207, 2018). "In the metastasis, of mice treated with the combination, both EGFR and uPAR/α5β1 integrin pathways are turn off; and tumor angiogenesis, a process influenced by these pathways, is reduced." (PMID 29844873, 2018). "An important mediator of tumor progression is EGFR, whose expression correlates positively with malignancy and contributes to poor prognosis." (PMID 30587839, 2018). "This work also confirmed the involvement of the EGF and CSF-1 paracrine loop in tumor cell migratory streaming by using erlotinib to block the EGFR on tumor cells or by using CSF1R antibodies to block the CSF1R on macrophages." (PMID 29599778, 2018). "One of the most studied examples is the EGFR and its ligands, which were found to induce both autocrine and paracrine loops that can enhance tumor growth, motility, invasion, metastasis and recruitment of tumor associated macrophages (TAM)." (PMID 30344941, 2018). "In this study we describe a novel role for BAG3 in driving tumour proliferation in TNBC by stabilising EGFR signalling transduction pathways." (PMID 29644001, 2018). "In many cases, EGFR genetic alterations determine abnormal EGFR trafficking, which contributes to increased signaling and tumor development." (PMID 29124875, 2018). "A recent study also reported that treatment with cetuximab, a clinically used anti‐EGFR antibody, led to significantly reduced tumor formation after intratibial injection of 143b cells." (PMID 30361264, 2018). "Inhibition of EGFR by tyrosine kinase inhibitors such as gefitinib and erlotinib has increased tumor response and prolonged patients' survival." (PMID 29713646, 2018). "The in vivo specificity of [68Ga]Ga-DFO-ZEGFR:2377 binding to EGFR in tumor xenografts was evaluated by presaturation of receptors using the monoclonal antibody cetuximab in tumor." (PMID 30231504, 2018). "After that, several other studies investigated the diagnostic accuracy of ctDNA in NSCLC patients who progressed to prior EGFR-TKIs, showing a very wide range of concordance rate with the tumor tissue analysis." (PMID 30190486, 2018). "Receptor-mediated (EGFR) adverse cutaneous effects result in dose reduction or discontinuation of treatment, limiting the effectiveness of tumour therapy." (PMID 30301942, 2018). "Tumor-derived exosome from lung tumor cells contain EGFR and uptake of TEX by ECs can trigger EGFR-dependent responses which are accompanied by the autocrine activation of VEGF receptor 2 (VEGFR-2) and elevated VEGF expression promoting angiogenesis." (PMID 29720982, 2018). "This echoes one of the recent findings that EGFR‐TKI‐resistant SCLCs can branch out from early events that pre‐existed in NSCLC prior to transformation based on tumour biopsy analysis." (PMID 29848757, 2018).
tumor (continued). "In tumor xenograft formed from miR-548k overexpression cells, EGFR and phosphorylation of Akt were consistently higher than that in control counterparts." (PMID 30131072, 2018). "Expression of these receptors, as well as the importance of EGFR amplification in tumor processes in GBM, gives strong evidence that NT also acts through these receptors in this type of tumor." (PMID 29467963, 2018). "Since EGFR was highly expressed on the tumor cell surface, MGO-PEG-CET was used for dual targeted delivery an anticancer drug doxorubicin (DOX)." (PMID 29584656, 2018). "EGFR is thought to play a role in the regulation of cell proliferation, its activation stimulates tumour growth and progression, promotes proliferation, angiogenesis, invasion, metastasis and inhibition of apoptosis." (PMID 30054711, 2018). "All of the EGFR-positive CTCs were detected in patients with an EGFR wild-type primary tumor, indicating a strong heterogeneity of EGFR expression also between the primary tumor and CTCs." (PMID 30572662, 2018). "MiR-7 downregulates the expression of epidermal growth factor receptor (EGFR) mRNA and protein and participates in tumor regulation as a regulator of EGFR." (PMID 30400981, 2018). "The epidermal growth factor receptor (EGFR) is another well-recognized tumor-specific antigen capable of targeting EpCAM-negative CTCs." (PMID 30539365, 2018). "Nuclear transport of EGFR is mediated by vesicular trafficking protein Vps34, and EGFR is recruited to the Arf promoter to repress the transcription of Arf tumour suppressor." (PMID 29615051, 2018). "Recent studies demonstrated that Fn14 upregulation correlates with EGFR phosphorylation (activation) in tumor cells." (PMID 30648117, 2018). "Using the AOM-DSS model here, which allowed for experimental separation of tumor initiation/early promotion from late promotion, we demonstrated that the protective effect of EGFR signaling is temporally governed." (PMID 29904166, 2018). "Apoptotic cells markedly increased in cetuximab-treated TE-8 tumors compared to isotype (p < 0.001), indicating that cetuximab treatment increased apoptosis in high-EGFR-expressing TE-8 tumor." (PMID 30373221, 2018). "In its absence, the effects of MEK inhibitors have been studied in tumors expressing mutated BRAF and KRAS; however, they led to tumor resistance through feedback and crosstalk mechanisms within the EGFR/MAPK and EGFR/PI3K signaling pathway." (PMID 29907857, 2018). "EGFR signaling through receptor phosphorylation and activation of downstream effectors contributes to tumor cell proliferation, apoptosis evasion, angiogenesis and metastasis." (PMID 29492209, 2018). "Membrane rafts are involved in EGFR signaling, and it has been shown that the activation of this pathway by membrane-raft domains in tumor and cholesterol depleting agents has both kinds of effects on GF receptor-mediated signaling." (PMID 30186863, 2018). "Several reports support this model; for example, in lung cancer prompt NF-κB activation upon EGFR inhibition is responsible for tumor cell survival and treatment failure." (PMID 30261609, 2018). "This demonstrates the feasibility of using targeted nanoparticle agents for the detection of surface receptors upregulated on tumor cells, including tumors overexpressing EGFR." (PMID 30408128, 2018). "With the increasing depths of ESCC tumor invasion there was a declining and rising trend in EGFR and MSI1 expression, respectively." (PMID 30202417, 2018). "The functional consequence of such a disruption of balance between membrane and nuclear EGFR signaling and its relation to the tumor-suppressing action of miR-145, however, warrant further investigation." (PMID 29459716, 2018). "It has been shown that tumor cells negative for the target molecule of the engager (in this case EGFR) were lysed when in proximity to tumor cells that display the target antigen through T-cell induced bystander cell lysis." (PMID 29755464, 2018).
tumor (continued). "The cobas EGFR test recommends macrodissection of low-percent tumor tissues (below 10%) to improve detectability." (PMID 29323170, 2018). "Yang and colleagues have evaluated EGFR gene status in tumor-derived free DNA in CSF to test correspondence with the molecular pattern of the primary tumor and to guide the clinical use of EGFR-TKI." (PMID 29881714, 2018). "Only 9/61 (14.8%) showed a high EGFR expression, whereas 41.0% (21/61) only showed a staining in less than 50% of tumor cells, indicating that only a subpopulation of tumor cells overexpress EGFR." (PMID 29848954, 2018). "As shown by small animal PET/CT the [64Cu]Cu-α-EGFR-EGFR-NODAGA TM enriched at the tumor site already after 2 h." (PMID 29876011, 2018). "First, EGFR retargeting is indispensable to achieve tumor-specific gene delivery in the A431 subcutaneous xenograft, demonstrating the functionality of the adapter." (PMID 29386504, 2018). "An interesting finding of our study is the paradoxical effect of miR-145, a well-established tumor-suppressing miRNA, on EGFR endocytosis." (PMID 29459716, 2018). "This clinical relevance is partly due to S100A9+ MDSC-derived macrophages in the tumor microenvironment, which attenuate the cytotoxic effect of EGFR-TKIs on otherwise sensitive cancer cells." (PMID 29484139, 2018). "Western blot analyses were performed to assess the expression level of total and phosphorylated forms of EGFR in tumor homogenates derived from the control and MAG-EPA-treated mice." (PMID 28869531, 2017). "Dysregulation of EGFR signaling has been shown to stimulate tumor cell proliferation, inhibit apoptosis, and promote angiogenesis and metastatic spread; and aberrations of the EGFR pathway are a common feature of HNSCC and are associated with worse prognosis." (PMID 31093353, 2017). "The Hippo pathway in turn interacts with several signaling cascades including TGFβ, WNT, EGFR/mitogen-associated protein kinase (MAPK), and others to regulate cell proliferation, tissue growth, apoptotic resistance, and tumor progression." (PMID 28649369, 2017). "This difference of anti-tumor effect in OE-21 cell line can be explained by the enhanced capability of Sym004 to induce EGFR internalization and degradation." (PMID 28038457, 2017). "Since nuclear EGFR is a hallmark of cancer aggressiveness, our findings reveal a novel mechanism for the contribution of PGE2 to tumor progression." (PMID 28415726, 2017). "We confirmed that the tumor tissues, as well as the cells cultured from them, were positive for EGFR-PPARGC1A by RT-PCR with fusion-specific primers." (PMID 28978917, 2017). "This again supports the concept of combining targeted therapies in NETs, as previously shown to be effective: Combined inhibition of mTORC1/2, PI3K/mTORC1/2, PI3K/mTORC1/2/ERK or EGFR/PI3K/mTORC1 has shown promising anti-tumor potential in NETs in vitro." (PMID 28800359, 2017). "Cetuximab (Erbitux®) is a DNA recombinant mAb that binds selectively to the extracellular domain of EGFR (encoded by HER-1) with a 5 to 10-times higher affinity than endogenous ligands, inhibiting the EGFR pathway and tumor growth." (PMID 28708103, 2017). "An example is the epidermal growth factor receptor (EGFR), which is overexpressed in several tumor types including breast, colon and non-small cell lung cancer (NSCLC)." (PMID 28405842, 2017). "This review will elaborate the possible mechanism of the interaction of immune cells on EGFR-TKIs in the tumor microenvironment, in order to seek new targets, and further improve the anti-tumor efficacy and prolong the effective time of EGFR-TKIs." (PMID 29167008, 2017).
tumor (continued). "To gain a precise insight into distinct sequences of targeted agents, we compared initial cetuximab (arm A) followed by VEGF-targeted therapy with initial bevacizumab (arm B) followed by EGFR-targeted regimens with respect to primary tumor sidedness." (PMID 29285289, 2017). "About 50% of TNBC tumours overexpress EGFR, which is correlated with poor prognosis in TNBC patients." (PMID 28593948, 2017). "EGFR plays an important role in immune cell regulation in the tumour microenvironment, and has been a therapeutic target for many cancers." (PMID 28541302, 2017). "The combined ORs indicated that high EGFR expression was significantly correlated with tumor differentiation, lymph node metastasis, and tumor stage." (PMID 28199988, 2017). "EGFR overexpression occurs in many solid tumors, and is correlated with tumor progression and metastasis, poor prognosis, and resistance to chemo- and radiotherapy." (PMID 28703807, 2017). "Its estimates are based on patient, lifestyle, tumor, and treatment characteristics, and EGFR status." (PMID 28969629, 2017). "Since the anti-tumor effect of theliatinib correlated with EGFR expression levels in the PDECX models, patient selection is important for beneficial outcomes." (PMID 28881608, 2017). "NSCLC tumor cells interact with their surrounding cellular tumorigenic network via EGFR signaling and other cell surface receptors that contribute to survival, proliferation, induction of tumor promoting factors and immune evasion." (PMID 28402937, 2017). "We have demonstrated that Tregs in HCC and other human tumour tissues are increased upon the expression of lnc-EGFR, suggesting that the lnc-EGFR-Treg axis is a common pathway during the pathogenic process of tumorigenesis." (PMID 28541302, 2017). "The fluorescence lifetime of eGFP (Picchu-X biosensor) in untreated tumours was 1.44±0.04 ns (Mean±s.e.m., N=15) suggesting active EGFR in situ, as observed by donor fluorescence lifetime quenching of the Picchu-X biosensor." (PMID 28166195, 2017). "Tumor cells in general show high levels of activation in the mitogen-related pathways, for example activation of the EGFR, which acts as a potent mitogen." (PMID 28879167, 2017). "First, EGFR-dependent tumor growth of HSC3 xenografts is driven mainly by the activity of the ERK1/2 signaling pathway because when few EGFRs are activated only the ERK1/2 axis is significantly activated." (PMID 29268862, 2017). "Here, the authors demonstrate that inhibition of cell cycle regulators CDK4/6 or MAPK blockade enhances the efficacy of EGFR inhibitors for these tumours in mice." (PMID 28059068, 2017). "One case (#25, gene amplification) showed a 78-fold increase of EGFR mRNA expression in the primary tumor and an up to 127-fold increase in the metastasis." (PMID 28199979, 2017). "Conventionally, tumor markers such as the EGFR expression level and copy number change are identified through IHC staining, PCR, or FISH analysis with specimens obtained from surgical resection or biopsy." (PMID 29166921, 2017). "MWA was conducted at the primary tumor sites, followed by EGFR-TKIs in the MWA plus EGFR-TKIs group." (PMID 28915624, 2017). "Here we report the molecular mechanisms by which PGE2 regulates EGFR nuclear translocation and the contribution of this signaling cascade to sustain tumor growth." (PMID 28415726, 2017). "The results obtained in this study can be explained by the remarkable increase of BLM uptake by targeted sonoporation following EGFR-MBs specific binding to tumor cells." (PMID 28938010, 2017). "Both Nbs showed potent antagonistic effects in vitro, as well as an inhibition of the tumor growth in vivo in case of a trivalent biparatopic anti-EGFR Nb 7D12-9G8-Alb." (PMID 29163515, 2017). "Sveral key components of this pathway, including PI3K, AKT, epidermal growth factor receptor (EGFR) and Ras, have been observed to be frequently mutated in most tumor cells and are significantly related to the hyperactivation of this pathway." (PMID 29113424, 2017).
tumor (continued). "EGFR and HER2 have been implicated in promoting tumor cell proliferation and survival through the Ras-Raf-Mek-Erk (Ras-MAPK) pathway." (PMID 29113345, 2017). "In this study we demonstrated that tumors from the LLC cells present KRAS mutation with tumor overexpression of VEGF, EGFR and KRAS." (PMID 29285236, 2017). "p38 inhibition of tumor xenografts showed viable cells with robust EGFR expression, but at a state of relative growth and migration arrest." (PMID 28410196, 2017). "The tyrosine kinase c-MET acts as a tumor suppressor in NSCLC, and as a resistance mediator to erlotinib in EGFR-activating mutations." (PMID 29156837, 2017). "Our current study revealed that the cAMP-H3BO3 complex is a novel EGFR inhibitor which can inhibit tumor growth." (PMID 28915593, 2017). "A tumour can compensate for EGFR (HER1) blockade through the activation of alternative signaling pathways such as amplification of MET as well as through changes in tumour microenvironment." (PMID 28056859, 2017). "Small-animal PET imaging performed to evaluate the potential of 64Cu-PCTA-cetuximab as an immuno-PET imaging agent for EGFR expression level in SNU-1066 tumor-bearing mice." (PMID 29190900, 2017). "Intravital imaging of flank tumor xenografts after EGF-Rh injection revealed co-localization of EGFR-GFP and EGF-Rh in perinuclear vesicles and clusters located proximally or overlapping with the plasma membrane." (PMID 29268862, 2017). "The sizes and weights of the tumours in the Anti-EGFR-CIL-miR-135a group were obviously reduced in comparison to the control (p < 0.001), miR-135a (p < 0.001) or LCL-miR-135a groups (p < 0.01)." (PMID 28729631, 2017). "Recently, several EGFR-targeting drugs have been developed to inhibit these EGFR-induced effects on tumor cells, including tyrosine kinase inhibitors and monoclonal antibodies." (PMID 28427242, 2017). "For evaluation of EGFR and KRAS mutations we used tissue adjacent to the implants, LLC cells in culture and tumor implants." (PMID 29285236, 2017). "In this study, we have performed microRNA array analysis and identified miR-338-3p, a tumor suppressor, as a downstream effector of EGFR." (PMID 28703807, 2017). "Similar results were obtained by immunoprecipitation of tumor lysates with anti-EGFR antibody and immunoblotting with anti-β3 antibody showing that no integrin β3 band was detected in immunoprecipitates of EGFR in CL4 tumor lysates." (PMID 28425453, 2017). "To investigate if nimotuzumab induces killing of EGFR+ tumor cells, we purified NK cells from healthy donor PBMC by negative magnetic isolation (described in “Materials and Methods”)." (PMID 28674498, 2017). "This study used cell-free circulating tumor DNA (cftDNA) to evaluate the appearance of codon 12 MUTKRAS and p.T790MEGFR mutations in 33 advanced NSCLC patients progressing after an EGFR-TKI." (PMID 26799287, 2017). "In fact, it has been shown that the inhibition of wild type EGFR leads to a less invasive tumor type by switching to an angiogenic state, which shows that even shared mechanisms can be activated in an independent manner." (PMID 28629170, 2017). "Our results demonstrate that pre-targeting PEG engagerEGFR to EGFR overexpressing TNBC tumours can markedly enhance the therapeutic efficacy of PEGylated liposomal doxorubicin (Doxisome) with limited side effects as shown by body weight loss analysis." (PMID 28593948, 2017). "For example, epidermal growth factor receptor (EGFR) is over-expressed in some tumor cells and plays an important role in tumor progression." (PMID 28912497, 2017). "The findings presented in this study support a new model for the function of PGE2 in tumor growth control and adaptation to the microenvironment, in which the prostanoid regulates EGFR activity by inducing its nuclear internalization." (PMID 28415726, 2017).